WDR91 (WD repeat domain 91)
Description:
Functions as a negative regulator of the PI3 kinase/PI3K activity associated with endosomal membranes via BECN1, a core subunit of the PI3K complex. By modifying the phosphatidylinositol 3-phosphate/PtdInsP3 content of endosomal membranes may regulate endosome fusion, recycling, sorting and early to late endosome transport. It is for instance, required for the delivery of cargos like BST2/tetherin from early to late endosome and thereby participates indirectly to their degradation by the lysosome. May play a role in meiosis (By similarity).
Synonyms: HSPC049; SORF-1; SORF1
Tractability: Small molecule: a structure with a bound ligand is known. Antibody: UniProt places it where antibodies can reach, with high confidence. PROTAC: ubiquitination databases record sites on it; its protein half-life has been measured.
Target class: Reader; Epigenetic regulator; Methyl-lysine/arginine binding protein; WDR domain
Gene: Protein-coding gene on chromosome 7 (135,183,839 to 135,211,557, reverse strand). Ensembl gene ENSG00000105875.
Subcellular location: Early endosome membrane; Late endosome membrane
Pathways (Reactome):
Signal Transduction: CDC42 GTPase cycle
Gene Ontology:
Molecular function: phosphatidylinositol 3-kinase inhibitor activity; protein binding; phosphatidylinositol 3-kinase regulator activity
Biological process: early endosome to late endosome transport; regulation of protein catabolic process; ubiquitin-dependent protein catabolic process; negative regulation of phosphatidylinositol 3-kinase/protein kinase B signal transduction
Cellular component: cytosol; early endosome membrane; endosome membrane; late endosome membrane
Genetic constraint (gnomAD): Loss-of-function variants: 49 observed, 86.81 expected, observed/expected ratio (o/e) 0.56, 90% interval 0.45 to 0.72. The upper end of that interval is the gene's LOEUF score, 0.72, which puts it in group 2 of 6, group 1 being the genes least tolerant of losing a copy. Missense variants: 781 observed, 941.44 expected, observed/expected ratio (o/e) 0.83, 90% interval 0.78 to 0.88. Synonymous variants: 343 observed, 382.65 expected, observed/expected ratio (o/e) 0.9, 90% interval 0.82 to 0.98.
Homologues: Orthologues: chimpanzee WDR91 (99% identical), macaque WDR91 (99% identical), dog WDR91 (94% identical), guinea pig WDR91 (93% identical), pig WDR91 (93% identical), rabbit WDR91 (93% identical), mouse Wdr91 (92% identical), rat Wdr91 (92% identical), tropical clawed frog wdr91 (70% identical), zebrafish wdr91 (64% identical), Drosophila melanogaster CG6005 (13% identical), Caenorhabditis elegans sorf-1 (9% identical).
Diseases named in the same sentence as WDR91 in open-access papers:
WDR91 is named in the same sentence as 5 diseases in open-access papers, as found by Europe PMC text mining. Sharing a sentence is not in itself a finding about the gene and the disease. The quoted sentences say what the papers report.
reovirus infection (2 papers, 2022 to 2023). "Other intriguing hits include the dynactin‐stimulated tail interactor Wdr91, a Rab7 effector implicated in endosomal recycling and lysosomal function, as well as reovirus infection." (PMID 37872872, 2023). "Interestingly, WDR81 interacts with WDR91, which was also identified in our work and in another screen for proviral factors of reovirus infection." (PMID 35320319, 2022). "In addition to WDR81 and WDR91, our screen uncovered two other proteins, Rab7 and CCZ1, that are required for endosomal maturation and reovirus infection." (PMID 35320319, 2022).
tumor (1 paper, 2021). "The results showed that NEBL, PDGFRA and ZBTB4 were upregulated in OC tissues compared to in normal ovarian tissues, whereas WDR91 were downregulated in tumor tissues." (PMID 34484284, 2021).
WDR91 also shares sentences with these, for which no sentence is quoted: infection (2 papers); lymphoma (1); viral infection (1).